FRMPD2 (FERM and PDZ domain containing 2)
Description:
Functions as a scaffold protein and likely plays a role in N-methyl-D-aspartic acid receptor (NMDAR)-mediated synaptic excitatory transmission (By similarity). May be involved in synapse formation in cone photoreceptor cells (By similarity). May play a role in the regulation of tight junction formation. Binds phosphatidylinositol 3,4-bisphosphate (PtdIns(3,4)P2). May play a role in the regulation of NOD2-mediated NF-kappa-B activation in immune response.
Synonyms: PDZD5C; PDZK4; PDZK5C; MGC35285
Tractability: Antibody: UniProt places it where antibodies can reach, with high confidence; its Gene Ontology location is reachable by antibodies, with medium confidence. PROTAC: ubiquitination databases record sites on it.
Gene: Protein-coding gene on chromosome 10 (48,153,088 to 48,274,696, reverse strand). Ensembl gene ENSG00000170324.
Subcellular location: Cytoplasm; Basolateral cell membrane; Cell junction, tight junction; Postsynaptic density
Subcellular location (Human Protein Atlas): Golgi apparatus; Vesicles
Gene Ontology:
Molecular function: 1-phosphatidylinositol binding; protein binding
Biological process: bicellular tight junction assembly
Cellular component: basolateral plasma membrane; bicellular tight junction; apical part of cell; cytoplasm; plasma membrane; postsynaptic density
Genetic constraint (gnomAD): Loss-of-function variants: 73 observed, 93.79 expected, observed/expected ratio (o/e) 0.78, 90% interval 0.64 to 0.95. The upper end of that interval is the gene's LOEUF score, 0.95, which puts it in group 4 of 6, group 1 being the genes least tolerant of losing a copy. Missense variants: 1,109 observed, 1,059.9 expected, observed/expected ratio (o/e) 1.05, 90% interval 1 to 1.1. Synonymous variants: 404 observed, 401.34 expected, observed/expected ratio (o/e) 1.01, 90% interval 0.93 to 1.09.
Homologues: Orthologues: macaque FRMPD2 (95% identical), chimpanzee FRMPD2 (92% identical), rabbit FRMPD2 (74% identical), mouse Frmpd2 (71% identical), pig FRMPD2 (70% identical), rat Frmpd2 (70% identical), dog FRMPD2 (65% identical), zebrafish frmpd2 (23% identical), Caenorhabditis elegans frm-5.1 (21% identical), Caenorhabditis elegans frm-5.2 (21% identical). Paralogues in human: PATJ (16% identical), MPDZ (16% identical), LNX1 (9% identical), LNX2 (9% identical), STXBP4 (5% identical).
Diseases named in the same sentence as FRMPD2 in open-access papers:
FRMPD2 is named in the same sentence as 3 diseases in open-access papers, as found by Europe PMC text mining. Sharing a sentence is not in itself a finding about the gene and the disease. The quoted sentences say what the papers report.
breast carcinoma (1 paper, 2022). "Focussing on known breast cancer driver genes, we identified clonal mutations in PIK3CA and MAP2K4 in ML10_Abr, and a clonal mutation in FRMPD2 in ML1_Abr." (PMID 35053458, 2022).
FRMPD2 also shares sentences with these, for which no sentence is quoted: autosomal recessive disease (1 paper); cancer (1).